IRF4 (interferon regulatory factor 4)
Diseases named in the same sentence as IRF4 in open-access papers (continued):
Sharing a sentence is not in itself a finding about the gene and the disease.
ischemic stroke (5 papers, 2014 to 2025). A stroke disorder caused by obstruction of blood flow to the brain, due to thrombotic (local blood clot formation) or embolic (due to a blood clot or other material traveling from another site) event. "In conclusion, our data delineate a previously unrecognised pro-survival pathway after ischaemic stroke: IRF4 initiates SRF transcription in neurons, which in turn promotes the expression of a myriad of SRF-dependent neuroprotective factors." (PMID 24510125, 2014). "In addition, other paralogs of IRF6, such as IRF4, IRF5, IRF8, and IRF9, have been linked to neuronal survival following ischemic stroke." (PMID 40149423, 2025). "IRF4 was expressed in neurons, and induced by ischaemic stroke." (PMID 24510125, 2014). "Thus, we have shown that the IRF4–SRF axis is a novel signalling pathway critical for neuronal survival in the setting of ischaemic stroke." (PMID 24510125, 2014). "Thus, our results demonstrated the IRF4–SRF axis to be a novel signalling pathway critical for neuronal survival in the setting of ischaemic stroke." (PMID 24510125, 2014). "Therefore, we showed that IRF4-SRF was a novel neuroprotective pathway in ischaemic stroke with potential therapeutic applications." (PMID 24510125, 2014). "Together, our data indicated that neuronal IRF4 may be involved in ischaemic stroke." (PMID 24510125, 2014).
myeloid leukemia (5 papers, 2013 to 2025). A clonal proliferation of myeloid cells and their precursors in the bone marrow, peripheral blood, and spleen. "In murine models, the absence of IRF4 has been proven to exacerbate the progression of myeloid leukemia, reinforcing the essential role of IRF4 in blood disorders and presenting potential avenues for disease intervention and treatment." (PMID 40073065, 2025). "Therein, indicating IRF4 as a crucial miR-125-5p target in myeloid leukemia." (PMID 27517498, 2016). "Indeed, it has been shown that miR-125-5p induces tumorigenesis in myeloid cells through the repression of IRF4 mRNA and, above all, that the expression of a IRF4 derivative without miR-125-5p binding sites rescues miR-125-5p induced myeloid leukemia." (PMID 27517498, 2016). "In addition, ectopic expression of IRF4 does not seem to be a specific feature of lymphoid leukemia, but it also extends to myeloid leukemia, as it was in our AML group that the highest expression levels were observed." (PMID 23977280, 2013). "This could also highlight the role of IRF4 in early myeloid cell differentiation and, subsequently, in myeloid leukemia without maturation but, since the number of observed cases here is small, no such conclusions can be made at this point." (PMID 23977280, 2013). "Besides, IRF4 could have regulated myeloid and lymphoid hematopoietic differentiation, and absence of it would exacerbate the development of myeloid leukemia." (PMID 34996458, 2022).
T-cell lymphoma (5 papers, 2017 to 2022). "Here, we demonstrated that overexpression of wild-type IRF4 can cause the development of aggressive T-cell lymphoma." (PMID 35504924, 2022). "Our recent study using a transgenic zebrafish model also demonstrated that MYC is commonly upregulated in IRF4-induced T-cell lymphoma." (PMID 36077849, 2022). "Whilst the STAT3 Y640F mutation was distributed across T-cell NHL cases, specifically 7 ATLL, 1 NK/T-cell lymphoma (NKTCL) and 1 MF, the IRF4 K59R mutation was only seen in ATLL patients, consistent with the restriction of signature 17 to these patients." (PMID 33597573, 2021). "Recurrent translocations involving IRF4 locus were also identified in T-cell lymphomas such as PTCL-NOS and cutaneous ALCL." (PMID 29346274, 2018). "Overall, these data indicate that IRF4 sustains the oncogenic properties of STAT3 in T-cell lymphomas, and that its inhibition represents an alternative avenue to interfere with STAT3 signaling and offers promising therapeutic opportunities to treat and prevent drug resistance in ALCL patients." (PMID 29346274, 2018). "Moreover, it was previously shown that the large majority of primary ALCL patient samples stained positive for IRF4 irrespective of ALK translocations, thus suggesting an important role for IRF4 in the pathogenesis of T-cell lymphomas." (PMID 29346274, 2018).
breast tumors (4 papers, 2019 to 2021). "A recent study reported that IRF4 is expressed by PMN-MDSC as well as M-MDSC and that 4T1 breast tumors reduced the expression of IRF4 in both cell types." (PMID 32448983, 2020). "Decreased TRIM24 expression and increased expression of the M2 genes CCL17 and IRF4 were detected in macrophages isolated from breast tumors compared with their levels in adjacent normal tissues." (PMID 31554795, 2019). "In support of our findings, it is interesting to note that significantly higher methylation in IRF4 was previously observed in HER2+ breast tumors in relation to normal breast tissues, and that high IRF4 expression associates with improved outcome in HER2+ node-negative BC." (PMID 32855526, 2020).
cardiac hypertrophy (4 papers, 2015 to 2024). "They found that cardiac specific overexpression of IRF4 exacerbated pressure overload-induced hypertrophy, fibrosis, and dysfunction, whereas IRF4 knockout attenuated cardiac hypertrophy." (PMID 38665231, 2024). "The authors attributed this effect to a role for IRF4 in inducing the transcription of cAMP response element-binding protein (CREB) in cardiomyocytes, which is known to promote cardiac hypertrophy." (PMID 38665231, 2024).
Cerebral ischemia (4 papers, 2021 to 2023). Restriction of arterial blood supply to the brain associated with insufficient oxygenation to support the metabolic requirements of the tissue. "IRF5 and IRF4 balance each other, and reducing the expression of IRF5 can promote M2-type activation, increase IRF4 expression, inhibit the inflammatory response, and improve outcomes in cerebral ischemia." (PMID 37361996, 2023). "The expression of IRF4/5 in microglia is significantly higher in aged female mice compared to male mice, and this difference is further amplified by cerebral ischemia injury." (PMID 37361996, 2023). "Conversely, reducing IRF4 expression can lead to increased IRF5 expression, promote M1-type activation, exacerbate the inflammatory response, and lead to worse outcomes in cerebral ischemia." (PMID 37361996, 2023). "In young mice, the levels of IRF4 and CD206, anti-inflammatory factors such as TGF-β, IL-4, and IL-10, are significantly higher in the brain compared to old mice after cerebral ischemia." (PMID 37361996, 2023).
ischemia (4 papers, 2016 to 2023). A hypoperfusion of the BLOOD through an organ or tissue caused by a PATHOLOGIC CONSTRICTION or obstruction of its BLOOD VESSELS, or an absence of BLOOD CIRCULATION. "In summary, the present study explored several key molecular mechanisms for IRF5/IRF4 to regulate microglial response to ischemia." (PMID 33573200, 2021). "This is in agreement with the expression peak of IRF-4 at day 3, a key transcription factor of M2 polarization phenotype, whereas expression of IRF-8, a transcription factor of M1 polarization phenotype, increases within 72 h after ischemia." (PMID 27539642, 2016).
kidney damage (4 papers, 2023 to 2025). "Upregulation of methyltransferase 3 (METTL3) in the kidneys of SLE patients promotes IRF4 - mediated plasma cell infiltration, resulting in kidney damage." (PMID 41181096, 2025). "METTL3 induced kidney damage by promoting IRF4-mediated plasma cell infiltration in an m6A-dependent manner." (PMID 39835138, 2024). "Inducing kidney damage through promoting IRF4-mediated plasma cell infiltration via an m6A-dependent manner." (PMID 39835138, 2024). "Also, TLR4, AOC3, IRF4, and TNFAIP6 were not differentially expressed in non-drug-induced AKI models including IRI and UUO models, which was unexpected and additional evidence of the specificity of these hub genes in drug-induced kidney damage." (PMID 37063876, 2023).
Listeria monocytogenes infection (4 papers, 2016 to 2025). "Under homeostatic conditions and at the peak of an acute listeria infection, Irf4-/- mice showed a significant reduction of FoxP3+ Treg cells." (PMID 40726986, 2025). "Here, we use the Listeria monocytogenes infection model to analyze the role of IRF4 in TH1 cell differentiation and function." (PMID 27762344, 2016). "We used Listeria monocytogenes infection to characterize the function of IRF4 in TH1 responses." (PMID 27762344, 2016). "In a previous study, IRF4 knockout mice failed to provoke Th1 immune response against Listeria monocytogenes infections." (PMID 29698503, 2018).
mantle cell lymphoma (4 papers, 2016 to 2024). Mantle cell lymphoma is a rare form of malignant non-Hodgkin lymphoma affecting B lymphocytes in the lymph nodes in a region called the ``mantle zone''. "Through screening for molecular vulnerabilities of mantle cell lymphoma (MCL), we identified a set of transcription factors (TFs) including FOXO1, EBF1, PAX5, and IRF4 that are essential for MCL propagation." (PMID 36282572, 2022).
pancreatic cancer (4 papers, 2020 to 2023). "IRF4 have critical roles in the immunosuppressive tumour microenvironment, and the deficiency of IRF4 accelerates tumour growth and reduces survival in pancreatic cancer." (PMID 33949771, 2021). "In summary, we demonstrate that IRF4 plays an important role in shaping the immune cell composition in the TME of murine pancreatic cancer." (PMID 32448983, 2020). "This study demonstrates a critical role of IRF4 in the generation of an immunosuppressive tumor microenvironment in pancreatic cancer, which is independent of IRF4 expression in PMN-MDSC." (PMID 32448983, 2020). "Recently, we reported that downregulation of the transcription factor interferon regulatory factor-4 (IRF4) improved antigen sensitivity which enabled CAR T cells to target antigenlow pancreatic cancer cells that are not recognized by CAR T cells with physiological IRF4 levels." (PMID 38090558, 2023).
periodontitis (4 papers, 2012 to 2025). An acute or chronic inflammatory process that affects the tissues that surround and support the teeth. "These included interferon regulatory factor 4 and chemokine (C-C motif) ligand 18, which were also expressed at the protein level in gingival biopsies from patients with periodontitis." (PMID 23029519, 2012). "Two of these 50 upregulated genes, IRF4 and CCL18, were also detected at the protein level in periodontitis affected-tissues, supporting these genes as novel finds in the pathogenesis of periodontitis." (PMID 23029519, 2012). "The expression of two of the top 50 differentially upregulated genes, IRF4 and CCL18 where further investigated at the protein level in gingival tissue samples from five additional patients with periodontitis." (PMID 23029519, 2012). "Immunohistochemical analysis showed that the transcription factor IRF4 and the chemokine CCL18 were expressed at the protein level in gingival tissue from patients with periodontitis." (PMID 23029519, 2012).
peripheral T-cell lymphomas (4 papers, 2013 to 2025). "For example, expression of IRF4 is related to poor survival outcomes in peripheral T-cell lymphoma and chronic lymphocytic leukemia (CLL)." (PMID 33629212, 2021). "MUM1(multiple myeloma oncogene-1) also known as IRF4(interferon regulatory factor 4) is a member of the interferon regulatory factor family and has been suggested as a potential therapeutic target in Peripheral T-cell lymphoma (PTCL) due to its expression in T-cell lymphoma." (PMID 40973845, 2025).
Sepsis (4 papers, 2020 to 2025). Sepsis is defined as life-threatening organ dysfunction caused by a dysregulated host response to infection. "IRF4 expression is inhibited in sepsis, thereby macrophages polarize towards M1, the maintenance of inflammatory state leading to the occurrence of ALI." (PMID 38022571, 2023). "After the application of Dihydroquercetin or Dexmedetomidine, IRF4 is upregulated in sepsis mice models, and macrophages polarized towards M2, producing effective anti-inflammatory effects." (PMID 38022571, 2023). "This appears to be in contrast to the decrease in IRF4 levels measured in sepsis mice models." (PMID 38022571, 2023). "The subsequent development of sepsis is closely related to IRF4." (PMID 38022571, 2023). "Furthermore, the mregDC module was significantly diminished in Batf3-/- and Irf4-/- septic mice in comparison with wild-type mice with sepsis, reduction in Irf4-/- mice was notably greater." (PMID 35832091, 2022). "Since the intestinal barrier disrupts before sepsis we believe that changes in intestinal IRF4 expression and its impact on the internal environment may be important factors that have not yet been elucidated in our understanding of the mechanism of sepsis." (PMID 38022571, 2023). "In sepsis RGS1, along with IRF4 and GAPDH, were highly upregulated across all B cell populations compared to control cells." (PMID 41208955, 2025). "Hence the impairment in the expression of Blimp-1 and IRF-4 in other immune cells, including PECs, T, and B cells post, pneumonia should also be studied to explore the unknowns associated with the cost of resolution of ALI associated with pneumonia and the patients recovered from sepsis." (PMID 32849610, 2020).
squamous cell carcinoma (4 papers, 2019 to 2024). A carcinoma arising from squamous epithelial cells. "The SNP rs12203592, located in the IRF4 gene intron, is linked to pigmentation traits, hematological traits, squamous cell carcinoma, and smoking cessation." (PMID 39148655, 2024).
acute kidney injury (3 papers, 2019 to 2024). Sudden and sustained deterioration of the kidney function characterized by decreased glomerular filtration rate, increased serum creatinine or oliguria. "Likewise, in the acute phase of IRI, IRF4 acts as an endogenous regulator of myeloid cell activation, i.e., dendritic cells, suppresses TNF-α release from intrarenal myeloid cells, and thereby limits tubular cell necrosis, tissue inflammation, and acute renal failure 24 h and 5 days post-IRI." (PMID 31632388, 2019).
acute leukemia (3 papers, 2013 to 2023). A clonal (malignant) hematopoietic disorder with an acute onset, affecting the bone marrow and the peripheral blood. "IRF4 has been implicated in acute leukemia, and strongly associated with pigmentation traits such as sensitivity of skin to sun exposure, freckles, blue eyes, and brown hair color." (PMID 30442871, 2018). "In this study we investigate the transcript levels of IRF4 in the diagnostic samples of a cohort of 58 pediatric acute leukemia patients and 4 cell lines, including both ALL and AML, and compare them to those of healthy controls." (PMID 23977280, 2013). "Quantitative real-time RT-PCR methodology was used to investigate IRF4 expression in 58 children with acute leukemias, 4 leukemic cell lines and 20 healthy children." (PMID 23977280, 2013). "This implies that high IRF4 expression might be used as an additional prognostic marker of relapse at the diagnosis of childhood acute leukemias." (PMID 23977280, 2013).
adenoma (3 papers, 2014 to 2021). A neoplasm arising from the epithelium. "For example, IRF4 was among the candidate genes identified as methylated in CRC in three studies, including in adenomas and TCGA data demonstrates strong differential methylation between cancer and normal tissues." (PMID 24485021, 2014).
allergic rhinitis (3 papers, 2022 to 2024). Inflammation of the nasal mucous membranes caused by an IgE-mediated response to external allergens. "IRF4 can induce airway inflammation in allergic rhinitis by participating in inflammatory responses involving Th2, Th9, and macrophages." (PMID 38491484, 2024). "IRF4, a major regulator of M2 macrophage activation, has been demonstrated to be involved in the pathogenesis of allergic rhinitis and athma." (PMID 35697826, 2022). "The IL-9, PU.1, IRF4, and Th9 cell counts in AR patients are elevated in patients with allergic rhinitis compared with those in healthy controls." (PMID 36248862, 2022).
celiac disease (3 papers, 2018 to 2022). An autoimmune genetic disorder with an unknown pattern of inheritance that primarily affects the digestive tract. "Of note, the human homologs of four of the CD11b+ DC Runx3 targets, CD300LF, IFIH1, IRF4 and SLC22A5 (mouse Slc22a21) harbored SNPs associated with IBD, CD, UC and/or celiac disease and the two former genes are common Runx3 targets in RM and CD11b+ DC." (PMID 32453801, 2020). "Ten of these cDC2 high-confidence Runx3 targets were common to those in RM and human homologs of four, CD300LF, IFIH1, IRF4 and SLC22A5 (mouse Slc22a21) harbored SNPs associated with IBD, CD, UC and/or celiac disease." (PMID 32453801, 2020).
cervical cancer (3 papers, 2021 to 2025). A primary or metastatic malignant neoplasm involving the cervix. "Among them, low expression of IRF4 is associated with poor prognosis of cervical cancer." (PMID 34020619, 2021). "To investigate the biological relevance of genes within the NAGS model, we first analyzed the expression levels of CSF2RB, SEMA6B, and IRF4 in the TCGA cervical cancer dataset." (PMID 40564066, 2025). "As a transcription factor involved in the differentiation of immune cells, IRF4 may be a good entry point for studying the immune cells and tumor microenvironment of cervical cancer." (PMID 34020619, 2021). "From above concern, it can conclude that hsa_circ_0000301/hsa-miR-1228-3p/IRF4 may be involved in the occurrence and development of cervical cancer." (PMID 34020619, 2021). "Meanwhile, according to MCC scores from the CytoHubba plugin in Cytoscape, the top 5 cervical cancer-related genes were screened out (MEF2C, CXCL16, IRF4, OAS3, PTGER3)." (PMID 34020619, 2021).
chronic myeloid leukemia (3 papers, 2009 to 2025). "An abnormal inflammatory status in the bone marrow microenvironment of myeloproliferative neoplasms (MPNs) has recently been demonstrated; moreover, in chronic myeloid leukemia a downregulated expression of IRF4 has been found." (PMID 34952638, 2021).
cutaneous melanoma (3 papers, 2017 to 2023). A primary melanoma arising from atypical melanocytes in the skin. "Although IRF4 expression has been described in skin melanoma, it has not been previously reported in either primary or metastatic UM." (PMID 33008022, 2020).
lung adenocarcinoma (3 papers, 2017 to 2021). A carcinoma that arises from the lung and is characterized by the presence of malignant glandular epithelial cells. "The correlation analysis between IRF4 and immune cells infiltration in lung adenocarcinoma patients." (PMID 34195096, 2021). "Clinical characteristics of lung adenocarcinoma patients with IRF4-high and low expression." (PMID 34195096, 2021). "Immune related interferon regulatory factor 4 (IRF4) is a member of the IRF family, whereas the clinical significance and possible role of IRF4 in lung adenocarcinoma (LUAD) remains unclear." (PMID 34195096, 2021).
mycosis fungoides (3 papers, 2019 to 2022). Classical mycosis fungoides is the most common type of mycosis fungoides (MF), a form of cutaneous T-cell lymphoma, and is characterized by slow progression from patches to more infiltrated plaques and eventually to tumors. "IRF4+ T cells were identified in skin from mycosis fungoides lesions and mycosis fungoides cell lines." (PMID 30807238, 2019).